NACC1 (nucleus accumbens associated 1)
Diseases named in the same sentence as NACC1 in open-access papers (continued):
Sharing a sentence is not in itself a finding about the gene and the disease.
lymph node metastases (1 paper, 2024). "NACC1 expression was demonstrated in PAAD in correlation with the status of lymph node metastasis for N vs. N0 and N vs. N1." (PMID 39769395, 2024). "Differences in NACC1 expression were also demonstrated for the number of lymph node metastases (i.e., N vs. N0, N vs. N1, N0 vs. N2, and N0 vs. N3)." (PMID 39769395, 2024). "Furthermore, there have been no analyses of the effects of the number of lymph node metastases, gender, and body weight on NACC1 expression." (PMID 39769395, 2024).
metastatic tumors (1 paper, 2023). "Analysis of the GSE183947 dataset matched normal, primary, and metastatic TNBC samples found a significant upregulation of NACC1 mRNA level in primary and metastatic tumors compared to normal tissues." (PMID 37189841, 2023).
ovarian serous cystadenocarcinoma (1 paper, 2024). A malignant serous cystic epithelial neoplasm arising from the ovary. "Interestingly, ovarian serous cystadenocarcinoma showed statistically significant NACC1 expression in all analyzed races when compared to normal tissue." (PMID 39769395, 2024).
retinoblastoma (1 paper, 2022). A malignant tumor that originates in the nuclear layer of the retina. "Among them, miR-218-5p is a tumor suppressor miRNA, which can inhibit the progression of retinoblastoma by targeting NACC1 to inhibit AKT/mTOR signaling pathway." (PMID 35465266, 2022).
Spina bifida occulta (1 paper, 2013). The closed form of spina bifida with incomplete closure of a vertebral body with intact overlying skin. "The non-closure of the vertebral elements in Nacc1-/- mice is reminiscent of the spina bifida occulta, a birth defect in multiple species (including humans) that is characterized by a similar failure of the vertebrae to close at the midline." (PMID 23922682, 2013).
cancer (24 papers, 2013 to 2025). A tumor composed of atypical neoplastic, often pleomorphic cells that invade other tissues. "Nucleus accumbens-associated protein 1 (NACC1) has been implicated in various cancers; however, its role in tumorigenesis is complex and varies depending on the cancer type." (PMID 40584295, 2025). "The expression levels of NACC1 were also associated with the cancer stage in almost all of the analyzed tumors." (PMID 39769395, 2024). "Our results allow us to determine the role of NACC1 in cancers and its possible diagnostic and therapeutic potential." (PMID 39769395, 2024). "NACC1 has been described in the literature as a potential prognostic and diagnostic biomarker for many cancers." (PMID 39769395, 2024). "This study demonstrates that NACC1 is potentially involved in the pathogenesis, invasion, and immune response associated with many cancers." (PMID 39769395, 2024). "Nucleus accumbens associated protein 1 (NAC1) is a cancer-related transcriptional factor and is encoded by the nucleus accumbens associated protein 1 (NACC1) gene." (PMID 39769395, 2024). "One of the promising factors affecting cancer is the nucleus accumbens associated protein 1 (NACC1)." (PMID 39769395, 2024). "With regard to mRNAs, nucleus accumbens-associated protein 1 (NACC1) is engaged in cancer pathogenesis and evaluation, such as drug resistance development, cytokinesis promotion and "stem cell-like" phenotypes maintenance." (PMID 35672774, 2022). "NAC1, encoded by the NACC1 gene, promotes autophagy response, disables cellular senescence and binds to actin to regulate cancer cell cytokinesis." (PMID 34416910, 2021). "In human cancers, NACC1 upregulation is associated with disease aggressiveness, development of resistance to chemotherapeutic agents, and tumor recurrence in ovarian, endometrial, and cervical carcinomas." (PMID 23922682, 2013). "In addition, abundant data indicate the overexpression of NACC1 in various cancers, which is associated with cancer progression and high relapse rates, thus potentially indicating poor prognosis." (PMID 39769395, 2024). "Our study demonstrated that several cancer-related mutations in the BEN domain of NACC1 and BANP disrupt DNA recognition, which may provide some clues for their relevance to human malignancy and may inspire us to identify new therapeutic strategies." (PMID 39225042, 2024). "NACC1 is overexpressed in many human malignancies and can regulate the progression, metastasis, and drug resistance of cancer cells." (PMID 39898241, 2025). "NACC1 is abnormally expressed in cancer cells and activates the AKT-related signaling pathway, thereby exerting its biological function." (PMID 39898241, 2025). "Nucleus accumbens-associated protein 1 (NACC1), containing a BTB/POZ domain, is a transcription factor associated with cancer." (PMID 39898241, 2025). "Recently, nucleus accumbens-associated protein 1 (NAC1), encoded by the NACC1 gene, was identified as a carcinoma-associated BTB/POZ family member." (PMID 40430078, 2025). "The results revealed that NACC1 was expressed in almost all of the analyzed cancers, and its expression level correlates with different clinicopathological parameters." (PMID 39769395, 2024). "We checked the differences in the expression levels of NACC1 depending on the race of the patient for the analyzed cancers." (PMID 39769395, 2024). "In our studies based on the TCGA database, we decided to analyze the function of NACC1 in analyzed cancers." (PMID 39769395, 2024). "In the analysis of sex, differences in NACC1 expression were presented by the following cancers: kidney renal clear cell carcinoma, kidney renal papillary cell carcinoma, and liver hepatocellular carcinoma." (PMID 39769395, 2024). "NACC1 expression analyses were performed using The Cancer Genome Atlas (TCGA) data accessed from the University of Alabama at Birmingham Cancer (UALCAN) database, and the expression data were interconnected with clinicopathological parameters." (PMID 39769395, 2024).
cancer (continued). "There is a significant amount of data in the literature on the presence of NACC1 in various cancers." (PMID 39769395, 2024). "This means that NACC1 is important in every tumor stage, which is important for cancer therapy and significant for etiopathogenesis and further research in this direction." (PMID 39769395, 2024). "In our research, we aim to analyze the existing data on the occurrence of NACC1 in various cancers based on The Cancer Genome Atlas (TCGA) databases and correlate them with the available data from publications." (PMID 39769395, 2024). "Previous studies have revealed the oncogenic roles of NACC1, including the regulation of cancer cell cytokinesis and tumour suppressor inactivation." (PMID 39225042, 2024). "NACC1 presented different expression levels depending on the number of lymph nodes in almost all the analyzed cancers, in comparison to the normal samples." (PMID 39769395, 2024). "We and others have previously shown that NACC1 plays an oncogenic role in several forms of cancers by supporting cell survival in hypoxic environments." (PMID 37189841, 2023). "Nucleus-accumbens-associated protein-1 (NAC1) is a cancer-related transcriptional factor encoded by the NACC1 gene, which is amplified and overexpressed in various human cancers and has been appreciated as one of the top potential cancer driver genes." (PMID 37626718, 2023). "Our correlation-based target predictions indicate that regulatory unit of PI3K i.e., PIK3R3 and cancer-driving transcription factor NACC1 are probable targets of hsa-miR-23b." (PMID 32413978, 2020). "This includes pairs of hsa-miR-23b-3p and NACC1, a cancer-related transcription regulator, hsa-miR-23b-3p and PIK3R3, as well as hsa-miR-134-5p and INA gene that encodes neuronal intermediate filament involved in pituitary tumorigenesis." (PMID 32413978, 2020). "Several studies have shown that NACC1 has predictive value for cancer progression in ovary, uterus, and pancreatic ductal adenocarcinoma tumors." (PMID 30248959, 2018). "NACC1, which encodes NAC1, amplified region at ch19p13.2 in cancer was first observed in high-grade ovarian cancer." (PMID 29163184, 2017). "The implementation of NACC1 as a therapeutic target may improve the effectiveness of cancer treatments." (PMID 39769395, 2024). "Moreover, only a few cancers showed a differing expression of NACC1 between nodal metastasis statuses." (PMID 39769395, 2024). "NACC1, the gene encoding NAC1, is one of the most significant genes to show a positive correlation between DNA and RNA copy number in human cancers, suggesting that it plays a driver role in cancer development." (PMID 30248959, 2018). "Experimentally, abundant NACC1 protein is essential for the migration and motility of cancer cells, maintenance of cell survival, prevention of cell senescence, and activation of autophagy in the presence of cisplatin through the high mobility group B1 pathway." (PMID 30248959, 2018). "In addition, NACC1 plays diverse roles in cancer biology, facilitating tumor migration and invasion through epithelial-mesenchymal transition (EMT) and inferring drug resistance." (PMID 30248959, 2018). "Such large fluctuations in NACC1 expression between various cancers further suggest that it is not a good candidate as a diagnostic marker." (PMID 39769395, 2024). "This also emphasizes the role of NACC1 in the development of malignant tumors, regardless of the grade of the tumor." (PMID 39769395, 2024). "The expression of NACC1 also differed between normal tissue and tumors, regardless of body weight, in the same cancers (i.e., BLCA, CESC, CHOL, COAD, ESCA, and LIHC)." (PMID 39769395, 2024).
tumor (15 papers, 2018 to 2025). "S5, O and P), suggesting that NACC1 or FKBP10 loss suppresses tumor growth by augmenting antitumor immunity." (PMID 37406115, 2023). "Furthermore, our Western analysis on AKT pathway-associated gene expression in the NACC1-depleted tumor cells showed decreased expressions of phospho-PTEN, β-catenin, and cyclin-D1, which is consistent with the RNA-seq data." (PMID 37189841, 2023). "Taken together, our study firstly linked circRHOBTB3 with NACC1, autophagy, and tumor progression." (PMID 34416910, 2021). "Expression of NACC1 is reported to be associated with poor prognosis of carcinomas in several organs, including the ovaries, oral cavity, colon/rectum, pancreas, uterine cervix, and prostate, as well as hematological and melanocytic neoplasms." (PMID 30248959, 2018). "NACC1 is overexpressed in various malignancies, correlating positively with tumor progression and recurrence, suggesting a poor prognosis." (PMID 39898241, 2025). "First of all, we checked the expression levels of NACC1 in normal samples in comparison to tumor samples, divided into the three races." (PMID 39769395, 2024). "While this finding is consistent with the activation of antitumor immunity by NACC1 KD reported here, further studies are required to determine how NACC1 promotes tumor immune evasion depending on cell and tumor types." (PMID 37406115, 2023). "Of nine genes down-regulated by NR2F6 loss, NACC1 and FKBP10 were negatively correlated with the IFN-γ signature, while high NACC1 and FKBP10 expression was associated with poor overall survival, patterns seen upon tumor-intrinsic NR2F6 inactivation." (PMID 37406115, 2023). "In immune-competent mice, NACC1 or FKBP10 depletion attenuated tumor growth, 26.7% (sh336) to 37.6% (sh334) and 42.9% (sh876) to 46.8% (sh486), respectively." (PMID 37406115, 2023). "NACC1 is acknowledged to exert imperative property in chemotherapy resistance and growth of tumor cells." (PMID 35672774, 2022). "NACC1 promotes proliferation, migration and invasion, inhibits apoptosis of HCT116 cells, while these effects were rescued by miR-423-5p, indicating that the tumor-facilitator role of NACC1 in CRC was regulated by miR-423-5p." (PMID 35034547, 2022). "qRT-PCR analysis and Western blot analysis showed that the expression of NACC1 was significantly upregulated in 38 CRC tumor tissues compared with 38 matched adjacent tissues." (PMID 35034547, 2022). "FUS-mediated circRHOBTB3 functions as a tumor activator to promote PDAC cell proliferation by modulating miR-600/NACC1/Akt/mTOR axis regulated autophagy." (PMID 34416910, 2021). "Most of the available studies in the literature on NACC1 focus on its expression in a single analyzed tumor, which may suggest its spectacular and specific nature." (PMID 39769395, 2024). "To determine whether candidate NR2F6 effectors exhibit antitumor activity, we asked whether NACC1 and/or FKBP10 loss would phenocopy NR2F6 loss and attenuate tumor growth." (PMID 37406115, 2023). "In addition, NAC1 mRNA (which is encoded by NACC1), a transcriptional regulator of FASN in tumor cells, was also increased, as well as PLIN2 (perilipin 2) mRNA, which is involved in lipid droplet formation." (PMID 34206240, 2021). "And the circRHOBTB3/miR-600/NACC1 axis was associated with tumor size, vascular invasion and T stage of patients, and each element was independent prognostic factors for PDAC patients, foreboding that the circRHOBTB3/miR-600/NACC1 is correlated with PDAC prognosis." (PMID 34416910, 2021). "In addition, suppression of NACC1 enhances tumor cell migration and invasion ability." (PMID 30248959, 2018). "Our findings establish a tumor-intrinsic function for NR2F6 and identify NACC1 and FKBP10 as their downstream effectors in inhibiting antitumor immunity." (PMID 37406115, 2023). "Inhibition of NACC1 and FKBP10 in tumor cells enhances CD8+ T cell recruitment to limit tumor growth by a number of possibilities." (PMID 37406115, 2023).
tumor (continued). "Further univariate and multivariate Cox regression analysis showed that circRHOBTB3, miR-600 and NACC1 expression levels were independent prognostic factors for PDAC patients, as were the tumor size and clinical stages." (PMID 34416910, 2021). "Our data further demonstrated that circRHOBTB3 acts as a miRNA-sponge to maintain the expression level of miR-600-targeted gene NACC1, thereby increasing autophagic flux of PDAC cells for adaptation of tumor development through inhibiting Akt/mTOR pathway." (PMID 34416910, 2021). "However, after inhibiting miR-18a-5 in EVs, miR-18a-5p was lowered, levels of NACC1 mRNA, p-AKT and p-mTOR were elevated, the ability of EVs to inhibit tumor growth was obviously weakened, the number of lung metastatic nodules was raised (all P < 0.01)." (PMID 35672774, 2022). "The results showed the drug-resistant mice injected with EVs and cisplatin exhibited significantly elevated miR-18a-5p, diminished NACC1 mRNA, p-AKT, and p-mTOR, and reduced tumorigenesis ability, tumor volume and weight (all P < 0.01), and decreased number of lung metastatic nodules." (PMID 35672774, 2022). "Notably, the combined loss of NACC1 and FKBP10 further decreased tumor growth (by 52.8%) in immune-competent but not immune-compromised mice, again without altering cell growth in vitro." (PMID 37406115, 2023).
neurodevelopmental disorder (6 papers, 2022 to 2024). A behavioral and cognitive disorder with onset during the developmental period that involves impaired or aberrant development of intellectual, motor, or social functions. "were the first to associate a human Mendelian disease with a NACC1 variant, making it a plausible disease-associated gene, as numerous neurodevelopmental disorders have been increasingly linked to misregulated gene expression." (PMID 39421062, 2024). "Summarizing, we have been able to show, in addition to neurodevelopmental disorder-related defects, a clear renal injury of high penetrance in our viable Nacc1 KO mouse model." (PMID 37160609, 2023). "Considering the miRNA and piRNA target genes common to multiple samples, four were already present in SFARI database: NACC1, SMAD4, TNRC6B, and TTN, and their mutants are implicated in ASD and other neurodevelopmental disorders." (PMID 35405953, 2022).
mitochondrial disease (1 paper, 2024). "Before the genetic diagnosis of NACC1 c.892C>T (p.Arg298Trp), two patients (patients 3 and 4) were suspected of having primary mitochondrial disease and underwent a muscle biopsy." (PMID 38698576, 2024).
movement disorder (1 paper, 2024). Neurological conditions resulting in abnormal voluntary or involuntary movement, which may impact the speed, fluency, quality and ease of movement. "The objective is to characterize the movement disorder in affected patients with the recurrent c.892C>T NACC1 variant and study the NACC1 protein and mitochondrial function at the cellular level." (PMID 38698576, 2024). "The movement disorder was analyzed on four patients with the NACC1 c.892C>T (p.Arg298Trp) variant." (PMID 38698576, 2024). "We suggest that NACC1 should be included in the gene panels for hyperkinetic movement disorders and be especially considered in patients with cyclical movement disorders." (PMID 38698576, 2024). "The movement disorder is a prominent feature of NACC1‐related disease." (PMID 38698576, 2024).
neurological diseases (1 paper, 2023). "As NACC1 had never before been associated with neurological diseases, we investigated how this mutation might lead to altered brain function." (PMID 37533751, 2023).
NACC1 also shares sentences with these, for which no sentence is quoted: cataract (2 papers); developmental delay (2); Ataxia (1); breast invasive carcinoma (1); Cerebral atrophy (1); developmental disability (1); Dyskinesia (1); Epileptic encephalopathy (1); genetic disorder (1); hepatocellular carcinoma (1); inflammatory bowel disease (1); intrahepatic cholangiocarcinoma (1); mantle cell lymphoma (1); microcephaly (1); Myoclonus (1); neurodegenerative disease (1); oral epithelial dysplasia (1); spindle cell tumors (1); squamous cell carcinoma (1); Tremor (1); undifferentiated sarcomas (1); unspecified (1); uterine corpus endometrial carcinoma (1).